CRP (C-reactive protein)
Diseases named in the same sentence as CRP in open-access papers (continued):
Sharing a sentence is not in itself a finding about the gene and the disease.
Stroke (continued). "Mo and colleagues found that in addition to lower Trp, KYNA and KAT activity, CRP levels and IDO activity were significantly higher among stroke patients compared to control individuals." (PMID 34680558, 2021). "IDO activity positively correlated with CRP, moreover, both CRP levels and IDO activity showed positive correlation with stroke severity." (PMID 34680558, 2021). "Another study also observed higher in-hospital mortality for patients with stroke and cancer with covariables of higher NIHSS and higher CRP at admission." (PMID 33945004, 2021). "For all stroke patients, age, stroke surgery history, NIHSS scores, PHQ-9 score, MMSE-K score, hs-CRP, and ESR were adjusted as confounding factors." (PMID 34828631, 2021). "Counts of WBC and neutrophil, level of IL‐6, and CRP were significantly higher in CE or LAA, supporting the role of chronic inflammatory mechanism in stroke." (PMID 33314753, 2021). "For patients with s/p stroke, considering F1 score, accuracy, and AUC, the combination of LDH, CRP, and α-HBDH showed the highest performance, followed by the combination of LDH and α-HBDH, then all five features." (PMID 34541519, 2021). "CRP, neutrophil count, and NLR within 24 h after stroke onset were significantly higher in patients with vs. without PSP." (PMID 34054712, 2021). "We found statistically significant differences on drinking, history of stroke or TIA, WBC, neutrophil count, lymphocyte count, C-reactive protein levels, NIHSS at admission, NIHSS score at discharge, and 3-month mRS between the two groups (P < 0.05)." (PMID 33330561, 2020). "The univariates affecting 2-year longevity were CHF, prior stroke, dialysis, ambulatory status, CLTI, BMI, total cholesterol, NLR, PLR, SII, CRP level, albumin, CONUT score, and GNRI." (PMID 33177036, 2020). "VB-stroke patients with GCA were older in age, had increased ESR- and CRP-values with decreased hemoglobin-values, and were more likely to have > = 2 vertebrobasilar stenoses/occlusions." (PMID 32323167, 2020). "Patients with severe stroke were significantly older, more frequently had atrial fibrillation, and had significantly higher serum levels of FBG, Hs-CRP and HCY." (PMID 31142624, 2019). "Moreover, the relationship between CRP trajectories and subsequent outcomes may have been mediated by incident chronic conditions such as coronary heart disease, stroke, or cancer occurring during the follow-up, which can have strong deleterious physical and mental health consequences." (PMID 29462285, 2019). "In stroke patients also, plasma gelsolin (pGSN) levels have been reported to decline significantly and a negative correlation with pGSN level was observed with the National Institute of Health Stroke Score/Scale (NIHSS) and C-reactive protein levels." (PMID 31002695, 2019). "At concentrations comparable to those reached in stroke patient plasma and found to correlate with severity of infarction, MMP‐13 can interact with both GPVI and αIIbβ3, and can compete with CRP and fibrinogen for occupation of these receptors." (PMID 30046741, 2018). "For example, vWF levels correlate with C-reactive protein (CRP) levels on admission;37however, data are conflicting concerning persisting elevation of vWF in the late phase after stroke." (PMID 29847840, 2018). "Serum CRP level was higher in infected patients than in uninfected patients, but IFN-γ level was lower in the infected patients on day 3 after stroke onset (both p < 0.05)." (PMID 27682880, 2017). "In the present study, for the first time, we developed a novel nomogram for prediction of CI-AKI based on ten readily available predictors (sex, DM, LDH, Hs-CRP, years since drinking, CKD, stage of CKD, stroke, acute MI, and SBP) at pre-procedure." (PMID 29088847, 2017).
Stroke (continued). "Adjusted logistic regression analysis revealed that infection was independently associated with splenic volume, leukocyte counts, the percentage of Treg cells, and the serum levels of CRP, IL-10, and IFN-γ on day 3 after stroke (all p < 0.05)." (PMID 27682880, 2017). "Several studies have shown that the percentages of cytotoxic T cells, natural killer (NK) cells, and B lymphocytes, and serum levels of TNF-α, IFN-γ, C-reactive protein (CRP), IL-4, IL-6, IL-10, and TGF-β are altered after stroke." (PMID 27682880, 2017). "On the other hand, systemic markers of inflammation, like CRP levels and WBC count have been shown to be predictors of stroke outcome." (PMID 28636639, 2017). "However, a dietary factor affecting CRP may not be relevant for modulating the risk of stroke since CRP is not on the causal pathway to ischemic stroke." (PMID 29255495, 2017). "As expected, stroke cases had increased levels of both serum IL6 and CRP compared to the control group; P < 0.01." (PMID 26945394, 2016). "He underwent a stroke workup including a complete blood count (CBC), erythrocyte sedimentation rate (ESR), C-reactive protein (CRP), carotid Doppler, echocardiogram, and magnetic resonance imaging/angiography (MRI/MRA) of his brain." (PMID 27802835, 2016). "The recent, multicenter VIPS study (Vascular effects of Infection in Pediatric Stroke) enrolled 355 patients ages 29 days to 19 years with AIS and evaluated high sensitivity CRP (hsCRP) and serum amyloid (SAA) within one month of stroke symptoms." (PMID 27909385, 2016). "This study is conducted to compare the high sensitive C-reactive protein (hs-CRP) levels and the lipid profile parameters between stroke patients and control group and demonstrate correlation between markers, neurological deficit, and short-term outcome." (PMID 27648176, 2016). "On the one hand, this is consistent with our findings that CRP was associated with fatigue levels at six months after stroke but not beyond this time point; on the other hand, this suggests that other biomarkers than CRP could also be indicators for the association between PSF and inflammation." (PMID 26599129, 2015). "CRP, WBC and neutrophil count values were comparable in stroke patients within 6 hours and controls, however, they were elevated in stroke one week after the insult." (PMID 24597828, 2014). "Although inflammatory biomarkers, such as hs-CRP and neutrophils, have been reported to be useful in predicting clinical outcome after stroke, the Ox-LDL seems to to be a better predictor than hs-CRP or WBC counts after AIS in the present study." (PMID 24423248, 2014). "Serum YKL-40 and C-reactive protein (CRP) levels were monitored over time in AIS patients (n = 105) and compared with those of stroke-free controls (n = 34)." (PMID 23272150, 2012). "Despite significantly decreasing LDL cholesterol and CRP levels and reducing cardiovascular hospitalizations, rosuvastatin failed to reduce the primary outcome (death from cardiovascular causes, nonfatal myocardial infarction, or nonfatal stroke) or the number of deaths from any other cause." (PMID 22364136, 2012). "Copeptin, PCT, WBC and CRP-levels on admission predicted any infection, pneumonia and UTI in the acute phase of stroke." (PMID 23118979, 2012). "H-FABP, IL-1ra, IL-8, S100β, CRP and Troponin I concentrations were also significantly increased whereas MMP3 and E-selectin concentrations showed a reduction in stroke patients compared to controls (0.001<p<0.05)." (PMID 23028472, 2012). "Among ischemic stroke patients, copeptin, PCT, WBC and CRP measured on admission were predictors of infection in general, and specifically for pneumonia and UTI within 5 days after stroke." (PMID 23118979, 2012). "ADMA was positively correlated with IL-6 and CRP at 3 and 7 days and with TIMP-1 at 6 and 24 hours, 3 and 7 days after stroke onset." (PMID 23158556, 2012).
Stroke (continued). "Seventy nine percent of the low-CRP group had a mild stroke (NIHSS<7), whereas only 60% of the high-CRP group had a mild stroke." (PMID 19400931, 2009). "The most common stroke subtype in the high CRP group was TACI (29%), whereas in the low and medium CRP groups the most common presentation was PACI (41% and 49%)." (PMID 19400931, 2009). "Earlier community data from the Northern Manhattan Study reported that hs‐CRP did not independently predict incident stroke after multivariable adjustment, highlighting cohort‐level differences." (PMID 41567175, 2026). "Compared with the favorable outcome group, the poor outcome group had significantly higher age, admission National Institutes of Health Stroke Scale (NIHSS) score, C-reactive protein level, severity of white matter hyperintensity (WMH), and the degree of anterior cerebral artery (ACA) stenosis." (PMID 42175459, 2026). "Biomarker‐guided trials are ongoing, for example, studies testing anti‐inflammatory therapies in patients with elevated CRP (such as CANTOS and COLCOT in coronary disease), approaches that could be adapted for stroke." (PMID 41567175, 2026). "The association between CRP and outcomes in patients with large vessel occlusion (LVO) stroke receiving endovascular therapy (EVT) has not been fully elucidated." (PMID 40682467, 2025). "The results showed that SIRI and CRP were significantly higher in stroke patients than in non-stroke patients." (PMID 39958615, 2025). "Furthermore, CRP and NSE have demonstrated significant predictive value for early neurobehavioral outcomes and stroke severity, further supporting NSE’s clinical relevance in acute neurological injury." (PMID 40714984, 2025). "Similarly, the rise of plasma hs-CRP levels at admission was associated with poststroke fatigue (PSF) 6 months after stroke, indicating that these alterations might predict the development of PSF in stroke patients, which could affect the long-term outcome of stroke." (PMID 40308934, 2025). "Although not yet validated in stroke models, this mechanism introduces a promising therapeutic direction—targeting the structural biology of CRP rather than its systemic levels." (PMID 40649973, 2025). "Anomalies in external carotid ultrasonography (ECU), high C‐reactive protein (CRP) values greater than 3 mg/dL, and the lack of anterior circulation involvement were all found to be independently associated with GCA‐related strokes." (PMID 39817601, 2025). "CRP is one of the most extensively studied inflammatory biomarkers, yet its presence in stroke thrombi has not been previously investigated." (PMID 39910895, 2025). "Reductions in CRP levels similar to those observed in the current study have been reported following EAA administration in rehabilitative settings, such as dysphagic stroke patients and elderly patients undergoing post-surgical rehabilitation after hip fracture." (PMID 41003011, 2025). "These five risk factors were identified in the NHANES analysis, and the directions for HBP, CRP, and SBP were consistent with NHANES results, whereas the direction for Stroke was opposite, showing a significant negative association." (PMID 41340073, 2025). "Unlike traditional clinical scales such as NIHSS, which mainly assess neurological severity, or inflammatory biomarkers like CRP, the WBC/HDL ratio integrates both inflammatory and lipid metabolic pathways, offering complementary information that can enhance stroke prognosis prediction." (PMID 40371080, 2025). "Hs-CRP levels were similar in populations with or without coronary artery disease and stroke history (p = 0.49 and 0.45), but higher in those with peripheral vascular disease (p = 0.019)." (PMID 40004724, 2025).
Stroke (continued). "After adjusting for age, sex, operation level, history of stroke and CHD, anesthesia duration, drinking status, intraoperative hypotension, CRP, Hb, fluid and blood transfusion volume, urinary volume, bleeding volume, ASA, and other CHS components, two key protective factors were identified." (PMID 40703294, 2025). "In the prognosis assessment of IS, traditional biomarkers and scoring systems such as NIHSS (National Institutes of Health Stroke Scale), mRS (Modified Rankin Scale), CRP (C-reactive protein) and NLR (neutrophil to lymphocyte ratio) have been widely studied and applied." (PMID 40371078, 2025). "C-reactive protein (CRP), as an acute-phase protein, serves not only as an indicator of systemic inflammation but also as a crucial biomarker for evaluating prognosis post-stroke." (PMID 40066310, 2025). "With a mean of 18.5 mg/L (SD = 10.2), compared to 11.1 mg/L (SD = 7.8) in the non-stroke group, the stroke group had higher levels of C-reactive protein (CRP) (p < 0.001)." (PMID 40432651, 2025). "Despite variations in mean levels between individuals with stroke and those without, none of the biomarkers, serum ferritin, C-reactive protein, lactate dehydrogenase, or D-dimer, show a statistically significant difference in their levels." (PMID 41362543, 2025). "In contrast, CRP is a general inflammatory marker that reflects systemic inflammatory activity; however, it does not offer stroke-type specificity." (PMID 40949500, 2025). "Serum levels of TMEM166 (12.54 ± 3.74 ug/mL vs 38.01 ± 10.01 ug/mL, p<0.01), IL-6 (1.02 ± 0.27 pg/mL vs 3.08 ± 0.78 pg/mL, p<0.05) and CRP (1.64 ± 0.6 ng/mL vs 3.09 ± 1.38 ng/mL, p<0.05) after CEA in perioperative stroke patients were statistically higher than in patients within the control group." (PMID 37611898, 2024). "Furthermore, our analyses adjusted for several important confounders, including, stroke severity, OCSP, WCC, and CRP." (PMID 38794724, 2024). "The observed disparities between the two groups were as follows: age (p < .001), gender (p = .002), stroke severity (p < .001), TOAST (p < .001), smoking (p < .001), atrial fibrillation (p < .001), Hs‐CRP (p = .020), FBG (p = .023), FIB (p < .001), ALB (p < .001), and FAR (p < .001)." (PMID 38376013, 2024). "The results of meta-analysis based on 3893 participants showed that CRP concentrations were significantly higher in patients with cognitive decline after stroke compared to non-cognitive decline patients." (PMID 39634177, 2024). "Patients who received an intermediate dose of canakinumab had a reduced occurrence of the primary endpoint, a composite of cardiovascular death, nonfatal acute myocardial infarction, or nonfatal stroke, accompanied by a reduction in IL-6 and CRP." (PMID 38274622, 2024). "In all stroke groups, regardless of the presence of AF, an increase in proteins (CRP, LBP, and A1AG1) involved in the inflammatory response was observed in patients with stroke compared to the control group." (PMID 38886511, 2024). "In patients with LMCADundergoing revascularization, elevated baseline hs-CRP levels were stronglyassociated with subsequent death, myocardial infarction (MI), and stroke at 3years, irrespective of the mode of treatment." (PMID 39484111, 2024). "The C-reactive protein level did not correlatewith the severity of illness or the outcomes of stroke scores in cases of hemorrhagic stroke." (PMID 40092874, 2024). "In both types of stroke, there is a robust inflammatory reaction characterized by neutrophil and macrophage activation, along with the release of inflammatory mediators like tumor necrosis factor-α (TNF-α), interleukin-6 (IL-6), and C-reactive protein (CRP)." (PMID 39329013, 2024). "For instance, elevated CRP levels during stroke's acute phase hint at an augmented PSD risk, however, this does not directly delineate the specific interplay between CRP levels and PSD." (PMID 38377025, 2024).
Stroke (continued). "Conversely, the Leptotrichia genus, Leptotrichia sp., and Oribacterium sinus demonstrated a negative correlation with CRP levels, stroke severity, and poor functional outcome." (PMID 39238889, 2024). "While this is suggestive of a link between serum CRP, stroke, and dementia, the time course of the events is not clear." (PMID 39063013, 2024). "To conclude, our study provides evidence for the negative prognostic value of acute-stage CRP levels in stroke patients treated via MT." (PMID 37360331, 2023). "In the development of a predictive model for SAP, multivariate logistic regression analysis showed that independent risk factors for SAP were age ≥ 65 years, National Institute of Health Stroke Scale (NIHSS) score ≥ 7, nasogastric tube feeding, and C-reactive protein (CRP) ≥ 5.0 mg/dL." (PMID 38063586, 2023). "In contrast, CRP concentrations—a widely used biomarker for systemic inflammation in numerous studies—was only correlated with stroke severity at admission but had no predictive value." (PMID 37212886, 2023). "This is further supported by our study which confirmed infections within 72 h after stroke onset as a negative predictor for a good outcome at discharge, as well as high CRP levels at admission to be predictive for a poor outcome at discharge." (PMID 37941023, 2023). "In another series, double-negative CRP/ESR was present in 36% (9/25) of patients with stroke and 18% (3/16) of other GCA patients." (PMID 38130834, 2023). "Although some studies have explored underlying associations between C-reactive protein (CRP) levels and cognitive decline after stroke, consistent results have not been obtained." (PMID 37509012, 2023). "Multivariate analysis did not confirm a difference in CRP levels between GCA subgroups with stroke or amaurosis." (PMID 38130834, 2023). "As per the findings of the present study, the CRP levels were also significantly higher in non-surviving stroke cases compared to survivors." (PMID 37577267, 2023). "Therefore, we included inflammation-related indicators, such as CRP and WBC, and other stroke-related biochemical indicators." (PMID 37065924, 2023). "Patients with myocardial infarction and a CRP of ≥ 2 mg/l receiving IL-1β-specific neutralizing antibodies presented significantly lower rates of recurrent cardiovascular events and non-fatal stroke." (PMID 37212886, 2023). "Additionally, direct comparisons between CIRP and established biomarkers, such as C-reactive protein, IL-6, and TNF-α, should be conducted to assess their predictive value, sensitivity, and specificity for stroke outcomes." (PMID 37521290, 2023). "Subgroup analysis was conducted by stratification according to study type, age, region, course of disease, C-reactive protein (CRP), erythrocyte sedimentation rate (ESR), the Bath AS Disease Activity Index (BASDAI), and the modified Stroke AS Spine Score (mSASSS)." (PMID 37503346, 2023). "RCS regression indicated that among subjects with normal hs-CRP, ApoB displayed a non-linear pattern with stroke, TC and LDL-C displayed a non-linear pattern with CHD, and ApoB displayed a non-linear pattern with CHD and CVD (all P < 0.05)." (PMID 37403063, 2023). "The subgroup analysis based on sample size showed that the correlation of hs-CRP levels with recurrent stroke and poor prognosis was not significantly affected by sample size." (PMID 37342777, 2023). "The primary analysis in our meta-analysis of nine studies revealed that, compared with non-CD patients, concentrations of CRP in the acute stage of stroke were higher in patients with CD than those in patients without CD." (PMID 37509012, 2023). "We included 87 patients with an ischemic stroke, whose medical records were retrospectively examined for background information (age, gender), stroke side and severity by NIHSS, length of stay in hospital, inflammation such as C-reactive protein, and vagal nerve activity." (PMID 37048532, 2023).